AZGP1 (alpha-2-glycoprotein 1, zinc-binding)
Diseases named in the same sentence as AZGP1 in open-access papers (continued):
Sharing a sentence is not in itself a finding about the gene and the disease.
Cirrhosis (3 papers, 2012 to 2021). A chronic disorder of the liver in which liver tissue becomes scarred and is partially replaced by regenerative nodules and fibrotic tissue resulting in loss of liver function. "Significant correlations were found between AZGP1 expression and three parameters including serum AFP levels (P = 0.013), cirrhosis (P = 0.002) and tumor differentiation (P = 0.017)." (PMID 22625427, 2012).
delirium (3 papers, 2019 to 2024). A disorder characterized by confusion; inattentiveness; disorientation; illusions; hallucinations; agitation; and in some instances autonomic nervous system overactivity. "Interestingly, they found that lower levels of AZGP1 were associated with a higher risk to develop post-surgical delirium in geriatric patients." (PMID 34083628, 2021). "We previously used mass-spectrometry-based plasma proteomics to define a preoperative delirium multi-protein signature that includes zinc-alpha-2-glycoprotein (AZGP1) and c-reactive protein (CRP) and a postoperative signature of interleukin-6 (IL-6), interleukin-2 (IL-2), and CRP." (PMID 39199312, 2024). "Finally, AZGP1, MMP-9, neopterin, phenylalanine–tyrosine ratio, SERPINA3, thioredoxin, and 8-iso-prostaglandin F2α were linked to postoperative delirium." (PMID 31263968, 2019).
morbid obesity (3 papers, 2015 to 2022). An excess of body weight, normally defined as an individual with a body mass index greater than 35 or a body weight greater than one hundred percent of ideal body weight. "We propose that the siblings' phenotype results from the combined effects of mutations in both AP4M1 and AZGP1 that account for the neurological signs and the morbid obesity of early onset, respectively." (PMID 26029708, 2015). "Altogether, our results suggest that the phenotype observed in our patients results from the additional effects of AP4M1 and AZGP1 mutations accounting for the neurological signs on one hand and the precocious morbid obesity on the other hand." (PMID 26029708, 2015).
pancreatic ductal adenocarcinoma (3 papers, 2012 to 2023). An infiltrating adenocarcinoma that arises from the epithelial cells of the pancreas. "A study found that the loss of AZGP1 expression was caused by histone deacetylation in pancreatic ductal adenocarcinoma." (PMID 37669935, 2023).
periodontitis (3 papers, 2017 to 2026). An acute or chronic inflammatory process that affects the tissues that surround and support the teeth. "Similar to FGF2, but with less prior evidence in relation to periodontitis, AZGP1, a class I major histocompatibility complex domain glycoprotein, showed strong evidence at all phases of our analysis." (PMID 40913361, 2026). "For reference, these correspond to a relatively moderate rank of 204 (FGF2), 645 (AZGP1) and 815 (BTC) among 3242 proteins that have shown any association with periodontitis." (PMID 40913361, 2026). "Previously, elevated levels of AZGP1 have been reported in the unstimulated saliva of patients with periodontitis." (PMID 40913361, 2026). "This study identifies three circulating proteins—FGF2, AZGP1 and BTC—as causally associated with periodontitis, highlighting their potential as therapeutic targets." (PMID 40913361, 2026). "AZGP1 participates in the pathogenesis of periodontitis by aggravating macrophage M1 polarization and pyroptosis through the NLRP3/caspase-1 pathway.signaling pathway." (PMID 38800469, 2024). "AZGP1 emerges as a critical mediator linking macrophage dysfunction, inflammation and periodontal tissue destruction, positioning it as a potential therapeutic target for the treatment of periodontitis." (PMID 40913361, 2026). "The Open Targets association scores for these proteins were 0.57 for FGF2, 0.20 for AZGP1 and 0.15 for BTC, providing additional context for their potential biological relevance to periodontitis." (PMID 40913361, 2026). "Further scrutiny examining colocalisation and directionality, and considering known protein interactions and prior evidence, suggested FGF2, AZGP1 and BTC as key targets for periodontitis." (PMID 40913361, 2026). "The lack of further research on the relationship between AZGP1 and periodontitis makes this an interesting and novel drug target that warrants future examination." (PMID 40913361, 2026). "Therefore, our findings support a potential causal role of FGF2, AZGP1 and BTC in the aetiology of periodontitis, rather than quantifying the precise clinical magnitude of their effects." (PMID 40913361, 2026).
preeclampsia (3 papers, 2013 to 2020). Preeclampsia is a hypertensive disorder of pregnancy that is characterized by new-onset hypertension with proteinuria presenting after 20 weeks of gestation, and depending on mild or severe forms may initially present with severe headache, visual disturbances, and hyperreflexia. "Other conditions associated with increased serum AZGP1 levels included preeclampsia and chronic heart failure, whereas decreased levels of AZGP1 were found in HIV patients." (PMID 23849457, 2013).
gastric tumor (2 papers, 2013 to 2021). "Consistent with the qRT-PCR results, a decrease in AZGP1 expression was observed in 25 (71.4%) of the gastric tumor tissues compared with the matched adjacent non-tumor tissues (P = 0.019)." (PMID 23935945, 2013).
head and neck cancer (2 papers, 2022 to 2023). A primary or metastatic malignant neoplasm affecting the head and neck. "AZGP1 is one of the most identified candidate biomarkers for PCa by numerous studies, as well as for bladder, colorectal, endometrial, pancreatic, head and neck cancer, and many others." (PMID 36553191, 2022).
heart failure (2 papers, 2013 to 2014). Inability of the heart to pump blood at an adequate rate to meet tissue metabolic requirements. "It has also been suggested that increased levels of AZGP1 in heart failure patients might be due to diminished renal function." (PMID 23849457, 2013).
kidney transplant (2 papers, 2019 to 2021). A surgical procedure in which one or both kidneys from a donor are implanted into a recipient. "Collectively, these results highlight AZGP1 as a new and promising therapeutic molecule for liver metastatic colorectal cancer." (PMID 31632499, 2019). "Together, this suggests that AZGP1 might be a potential biomarker for cardiovascular health in kidney transplant recipients and that it should be explored as a target for improving cardiovascular outcome." (PMID 34291094, 2021).
metastatic disease (2 papers, 2019 to 2020). "In this study of AZGP1 expression in PCa specimens from men with locally advanced or metastatic disease managed with first-line ADT, we found that AZGP1 expression was predictive of the development of CRPC." (PMID 32726925, 2020). "Four BD proteins, including PZ, AZGP1, SHBG, and VWF, were selected for further testing by ELISA using a cohort of 52 PDAC patients, including 19 stage III and 33 stage IV with metastatic disease." (PMID 31346328, 2019).
non-small cell lung carcinoma (2 papers, 2021 to 2023). A group of at least three distinct histological types of lung cancer, including non-small cell squamous cell carcinoma, adenocarcinoma, and large cell carcinoma. "Our previous research has shown that LINC00467 can activate the AKT signaling pathway by binding to AZGP1, leading to its degradation and promoting the progression of non-small cell lung cancer." (PMID 37078359, 2023). "Previously, our group found that LINC00467 can regulate the phosphorylation of AKT in non-small cell lung cancer by binding to AZGP1 to promote cancer cell migration and invasion." (PMID 34362879, 2021). "Previously, we found that LINC00467 could bind to AZGP1 and promote its degradation, activating the Akt signaling pathway to promote non-small cell lung cancer progression." (PMID 34362879, 2021).
rectal adenocarcinoma (2 papers, 2024). "Notably, AZGP1 has been linked to cancer cachexia, and TCGA datasets revealed elevated mRNA expression in colon adenocarcinoma (COAD) and rectum adenocarcinoma (READ)." (PMID 38245780, 2024).
renal fibrosis (2 papers, 2022 to 2024). A final common manifestation of a wide variety of chronic kidney diseases characterized by glomerulosclerosis and tubulointerstitial fibrosis. "For example, administration of exogenous AZGP1 to mice with ureteral obstruction decreases renal fibrosis, protecting against renal scarring and damage, implying it acts as a ligand in that it does not need to be expressed within a cell or tissue in order to show effects." (PMID 38659028, 2024).
triple-negative breast carcinoma (2 papers, 2022 to 2024). An invasive breast carcinoma which is negative for expression of estrogen receptor (ER), progesterone receptor (PR), and human epidermal growth factor receptor 2 (HER2). "The screen identified an adipogenic modulator, zinc-alpha-2-glycoprotein (ZAG/AZGP1) that is secreted by triple-negative breast cancer (TNBC) cells." (PMID 38888911, 2024).
Ureteral obstruction (2 papers, 2022 to 2024). Obstruction of the flow of urine through the ureter. "Here, we tested new opportunities for the therapeutic potential of AZGP1 using murine unilateral ureteral obstruction (UUO) as a fibrotic kidney disease model and evaluated potential implications of AZGP1 in renal lipid metabolism." (PMID 35054830, 2022).
all (1 paper, 2023). "In addition, the all-cancer meta-analysis across BBJ1 and UKB found a novel association (rs2525548 at AZGP1 on 7q22, P = 2.5 × 10−9)." (PMID 37340002, 2023).
chronic obstructive pulmonary disease (1 paper, 2025). A chronic and progressive lung disorder characterized by the loss of elasticity of the bronchial tree and the air sacs, destruction of the air sacs wall, thickening of the bronchial wall, and mucous accumulation in the bronchial tree. "AZGP1 has been reported to function as an RNA-binding protein that inhibits epithelial cell proliferation in the lung tissue of patients with chronic obstructive pulmonary disease, and its deficiency contributes to disease exacerbation." (PMID 40375315, 2025).
chronic pancreatitis (1 paper, 2025). A chronic inflammatory process causing damage and fibrosis of the pancreatic parenchyma. "For instance, AZGP1 and ALB were highlighted as potential diagnostic markers in chronic pancreatitis while ORM2 has been implicated in inflammatory pancreatic conditions." (PMID 41007761, 2025).
dry eye (1 paper, 2022). "For instance, LCN1, PIP, LTF, and SG2A1 were substantially reduced in dry eye, while AZGP1, LEG7, CST4, CST1, and ACTB were diminished in MGD." (PMID 35685417, 2022).
gastric adenocarcinoma (1 paper, 2013). "Kaplan–Meier survival curves revealed that the reduced expression of AZGP1 was associated with a poor prognosis in gastric adenocarcinoma patients (P = 0.009)." (PMID 23935945, 2013). "Multivariate Cox analysis identified AZGP1 expression was an independent prognostic factor for overall survival of gastric adenocarcinoma patients (HR = 1.681, 95% CI = 1.134–2.494, P = 0.011)." (PMID 23935945, 2013). "The immunohistochemical staining data showed that AZGP1 expression was significantly decreased in 52.8% (131/248) of gastric adenocarcinoma cases." (PMID 23935945, 2013).
keratoconus (1 paper, 2016). A degenerative, structural disorder of the eye, characterized by a cone-shaped protrusion of the cornea. "Albeit, recent studies have shown that matrix metalloproteinases MMP1 and 9, AZGP1, SFRP1, IGKC and cell adhesion molecules ICAM-1 and VCAM-1 to be specifically regulated in keratoconus, indicating their probable exclusive role in keratoconus." (PMID 27493978, 2016). "Tear analysis using a 2-DE/MS approach, identified zinc-α2-glycoprotein (AZGP1), immunoglobulin kappa chain, and lactoferrin (LTF) to be reduced in keratoconus." (PMID 27493978, 2016).
liver cirrhosis (1 paper, 2012). "Moreover, low expression of AZGP1 was notably more prevalent in patients with poor tumor differentiation, serious liver cirrhosis, high serum AFP level and short survival time." (PMID 22625427, 2012). "Furthermore, AZGP1 expression in HCC significantly associated with several clinicopathological parameters, including serum AFP level (P = 0.013), liver cirrhosis (P = 0.002) and tumor differentiation (P = 0.025)." (PMID 22625427, 2012). "Patients with low AZGP1 expression had a higher tendency to have high level of serum AFP, liver cirrhosis, and poor tumor differentiation." (PMID 22625427, 2012).
liver fibrosis (1 paper, 2025). "The APASHA model—consisting of APOF, PCSK9, AFM, S100A6, HbA1c %, and AZGP1—showed an excellent discriminatory capacity with an AUROC of 0.8875 (CI 0.82–0.96) to discriminate MASH, but not liver fibrosis." (PMID 40250425, 2025).
male infertility (1 paper, 2016). The inability of the male to effect fertilization of an ovum after a specified period of unprotected intercourse. "Both PATE4 and AZGP1 being proteins secreted into the extracellular environment, they might thus constitute appealing targets for the non-invasive diagnosis of male infertility." (PMID 27695046, 2016).
mucinous adenocarcinoma (1 paper, 2019). An invasive adenocarcinoma composed of malignant glandular cells which contain intracytoplasmic mucin. "The intensity of AZGP1 in mucinous adenocarcinoma was significantly higher than in non-mucinous adenocarcinoma (P=0.029)." (PMID 31632499, 2019).
myocardial infarction (1 paper, 2021). Gross necrosis of the myocardium, as a result of interruption of the blood supply to the area, as in coronary thrombosis. "Since the pathophysiologic relationship between AZGP1 and CV risk factors especially in older adults is still unclear, we focused in our analysis on the predictive power of AZGP1 and found AZGP1 to be predictive for mortality and the composite endpoint including myocardial infarction and stroke." (PMID 34083628, 2021).
nasal polyps (1 paper, 2022). "hsa-mir-27a-3p may promote the occurrence of inflammation and the formation of nasal polyps by regulating the expression of AZGP1, NCF2, CCL13, MUC7, PIP, and STATH." (PMID 36059464, 2022).
prostate tumor (1 paper, 2020). "It is possible that the better sampling of the prostate tumor by acquiring more biopsies for IHC analyses than the median of 4 in this study would be necessary to better assess the AZGP1 expression of the hole PCa." (PMID 32726925, 2020).
soft tissue sarcoma (1 paper, 2018). A malignant neoplasm arising from muscle tissue, adipose tissue, blood vessels, fibrous tissue, or other supportive tissues excluding the bones. "In summary, our study demonstrated that low AZGP1 expression was associated with higher invasive and metastatic cellular potentials in soft-tissue sarcomas." (PMID 29357838, 2018). "AZGP1 immunohistochemistry (IHC) and RT-PCR were performed in 86 patients with soft tissue sarcomas." (PMID 29357838, 2018). "The quantitative RT-PCR results showed that AZGP1 expression was negatively correlated with metastasis and overall survival in soft tissue sarcomas (p < 0.05)." (PMID 29357838, 2018). "The aim of this study is to determine the expression level of AZGP1 in soft tissue sarcomas, and to analyze its influence on tumor progression." (PMID 29357838, 2018). "AZGP1 is a potential biomarker of cancer progression, but its value in soft tissue sarcomas remains unknown." (PMID 29357838, 2018).
thyroid cancer (1 paper, 2021). "Meanwhile the six-gene model revealed that high expression of AZGP1 was negatively associated with prognosis in thyroid cancer, so it might also play a critical role in thyroid cancer." (PMID 33816259, 2021). "We found six RBPs (AZGP1, IGF2BP2, MEX3A, NUDT16, NUP153, USB1) independently associated with prognosis of patients with thyroid cancer according to univariate and multivariate Cox proportional hazards regression models." (PMID 33816259, 2021).
urinary bladder cancer (1 paper, 2012). A primary or metastatic malignant neoplasm involving the bladder. "AZGP1 was stage-dependent increased in the urinary bladder cancer." (PMID 22625427, 2012).
cancer (87 papers, 2006 to 2026). A tumor composed of atypical neoplastic, often pleomorphic cells that invade other tissues. "The highest diagnostic accuracy for discrimination between cancer vs. BPH was obtained when combining AZGP1, PEDF, and PSA (AUC = 0.85)." (PMID 30158500, 2018). "AZGP1 has functionally been implicated in lipid metabolism, the regulation of cell cycling and cancer progression." (PMID 23849457, 2013). "For this reason, AZGP1 is discussed as a useful diagnostic marker in various cancers." (PMID 39851496, 2025). "Additionally, previous studies indicated that a few cytokines or secreted proteins, such as AZGP1, were associated with lipolysis and browning, ultimately leading to cancer cachexia." (PMID 38245780, 2024). "Strikingly, over-expression of AZGP1 in PCa cells increased aggressive behavior, contradicting the many clinical studies demonstrating that loss of protein and RNA expression of AZGP1 are associated with cancer progression and mortality." (PMID 38659028, 2024). "So, the expression analysis of AZGP1 in two cases, smoking and cancer where one is the cause and the other is the effect, could not be correlated from our data." (PMID 33564003, 2021). "In some cancers, AZGP1 shows significant diagnostic value as a serum marker." (PMID 31632499, 2019). "AZGP1 was reported to be a diagnostic marker for cancer cachexia due to its high expression." (PMID 22625427, 2012). "AZGP1 has been reported to cause extensive loss of fat, often associated with advanced cancers." (PMID 21060876, 2010). "The up-regulated Azgp1 protein may serve as prognostic value, since it stimulates lipid degradation in adipocytes and causes the extensive fat losses associated with some advanced cancers." (PMID 40006055, 2025). "We elucidate the mechanism of cell death associated with the increased expression of soluble AZGP1 and report its potential as a predictive biomarker for therapeutic response to 5-fluorouracil treatment, as well as an immune activator in enhancing the efficacy of anti-cancer therapies." (PMID 41013181, 2025). "Here, we elucidate the mechanism of cell death associated with the increased expression of soluble AZGP1 and report its potential as a predictive biomarker for therapeutic response to 5-FU treatment, as well as an immune activator in enhancing the efficacy of anti-cancer therapies." (PMID 41013181, 2025). "The DEG AZGP1 as observed increases with increasing dietary oil inclusion; is related to stimulation of the breakdown of lipids within adipocytes, which causes fat to be lost in some advanced cancers; and is also capable of binding to polyunsaturated fatty acids." (PMID 35804531, 2022). "For example, in S3, AZGP1, up-regulated, is described in the literature as stimulating lipid degradation in adipocytes and causing the extensive fat losses associated with some advanced cancers and antigen processing and presentation of endogenous peptide antigen via MHC class Ib." (PMID 34771131, 2021). "We found that the loss of EHMT2 led to increased expression of AZGP1, culminating in the attenuation of TGF-β1, thereby facilitating an enhanced NK cell-mediated eradication of cancer cells." (PMID 41366520, 2026). "EHMT2 loss increased AZGP1 and decreased TGF-β1 levels, resulting in the autocrine elevation of NKG2D ligands MICB and ULBP3, chemokines in cancer cells, and the paracrine stimulation of NK cell function." (PMID 41366520, 2026). "For instance, AZGP1 is known to influence several cancer hallmarks including regulation of tumor proliferation, epithelial-mesenchymal transition, and infiltration of immune cells in tumor microenvironment." (PMID 40802546, 2025). "Accordingly, low expression levels of AZGP1 were found in various cancers, including prostate and liver, and correlates with a worse patient prognosis." (PMID 39851496, 2025). "Elevated soluble AZGP1 levels were shown to interact with PD-L1, enhancing apoptosis in cancer cells." (PMID 41013181, 2025).